INS (insulin)
Diseases named in the same sentence as INS in open-access papers (continued):
Sharing a sentence is not in itself a finding about the gene and the disease.
Hyperinsulinemia (continued). "The semi-maximal effect of insulin in suppressing whole-body protein degradation occurred approximately between 20 and 30 μU/mL of plasma insulin concentration, whereas the “maximal” effect was obtained by pharmacologic hyperinsulinemia (1000–1500 μU/mL)." (PMID 38201949, 2023). "Although hyperinsulinemia is considered a significant predictor of MS development, the inability to secrete insulin is strong evidence of pancreatic β-cell deterioration to external stimuli, such as high glucose concentrations for prolonged periods." (PMID 37887410, 2023). "In short-term human clinical investigations, chronic hyperinsulinemia has also resulted in acquired IR and downregulation of insulin signaling pathways." (PMID 37671098, 2023). "17α-E2 was also equally effective at improving hyperinsulinemia and insulin sensitivity in male WT and ERβKO mice in our study." (PMID 37330610, 2023). "Insulin-sensitizing agents such as metformin reduce serum androgen and gonadotropins and reduce hyperinsulinemia." (PMID 37514214, 2023). "A FINS/CP ratio of over 9.3uIU/ng (0.19 molar ratio) was shown to be a good indicator for screening IAs positive in insulin or insulin analog-treated patients with hyperinsulinemia in clinical practice." (PMID 37324170, 2023). "High insulin levels in hyperinsulinemia activate insulin/IGF signaling pathways followed by the activation of (PI3K)/Akt/mammalian rapamycin (mTOR) and MAPK signaling pathways, thus promoting cancer cell growth, survival, and mobility." (PMID 36834693, 2023). "On the other hand, obese patients are often accompanied by IR and hyperinsulinemia, and higher insulin induces the expression of vascular endothelial growth factor receptor (VEGFR), which promotes angiogenesis as well as the proliferation of endometrial cells." (PMID 37537560, 2023). "It is important to note that resveratrol’s positive effects on β-cells were also observed in type II diabetic patients, significantly lowering blood insulin levels in those with hyperinsulinemia." (PMID 37241737, 2023). "Insulin signalling contributes to both embryonic and postnatal cardiac growth, and even short-term in utero hyperglycaemic exposure induces fetal hyperinsulinemia and rapidly induces cardiac septal overgrowth via altered myocardial proliferation in rats." (PMID 37482780, 2023). "The role of insulin was further supported by recent experimental evidence in vitro showing that hyperinsulinemia induced early senescence in both human adipose and liver cells." (PMID 37317964, 2023). "Reduction in hyperinsulinemia: Hyperinsulinemia, characterized by elevated insulin levels in the bloodstream, is a common and consequential feature of PCOS." (PMID 38106751, 2023). "Insulin has been reported to promote glucose uptake in the muscles and physiological hyperinsulinemia has been shown to promote muscle protein synthesis and muscle anabolism." (PMID 37546289, 2023). "Impaired tissue sensitivity to insulin or IR paradoxically leads to diseases with an inflammatory component despite hyperinsulinemia." (PMID 37372966, 2023). "Use of a monolayer in vitro culture system has allowed our group to identify the isolated effects of hyperinsulinemia on insulin homeostasis within brain endothelial cells." (PMID 37834116, 2023). "Polycystic ovary syndrome (PCOS) is an insulin-resistant state compensated for by the body via hyperinsulinemia." (PMID 38068304, 2023). "Fasting plasma insulin concentration increased significantly in the diabetic model mice, and irisin intervention attenuated their hyperinsulinemia." (PMID 37993958, 2023). "Insulin resistance (IR), a pathological situation characterized by reduced tissue sensitivity to insulin and marked compensatory hyperinsulinemia, has continued to generate interest." (PMID 37378117, 2023). "But FC and Piog decreased the induced hyperinsulinemia significantly, suggesting increased insulin sensitivity." (PMID 37710214, 2023).
Hyperinsulinemia (continued). "Before getting to this metabolic condition, the insulin concentration is increased by pancreatic β cells, promoting hyperinsulinemia." (PMID 36626404, 2023). "Sedentariness also decreases insulin sensitivity in muscle, which results in hyperinsulinemia occurring to maintain normal glucose disposal." (PMID 37568405, 2023). "Hyperinsulinemia has strong anabolic effects leading to proliferative tissue abnormalities, DNA synthesis, and cell proliferation, which strongly suggests insulin’s role in cancer progression." (PMID 37373357, 2023). "A high dietary intake of SFA adversely impacts glucose and lipid metabolism by increasing hyperglycemia, hyperinsulinemia, and insulin resistance in metabolic organs such as the liver, pancreas, adipose tissue, and kidney." (PMID 37009872, 2023). "Along with increased insulin secretion, reduced insulin clearance is also a critical factor in hyperinsulinemia development." (PMID 36675244, 2023). "Foods with a high GI will increase the concentration of glucose and insulin in blood and thus induce hyperinsulinemia." (PMID 37346909, 2023). "A trend towards hyperinsulinemia and impairment of insulin sensitivity was observed in lean PCOS subjects, but these changes were only significant in obese PCOS patients." (PMID 36834549, 2023). "The continuation of hyperinsulinemia leads to the failure of β-cell function, which suggests that decreased insulin secretion in the patient’s mother resulted in an abnormal HbA1c level of 6.5%." (PMID 37042492, 2023). "Taken together, our data demonstrated that BRSK2 is both required and sufficient for hyperinsulinemia, likely in part via enhancing insulin secretion." (PMID 37188647, 2023). "While both Obese and Food matched groups displayed persistent hyperinsulinemia, Cmpd 1 animals appeared to have a reduction in insulin levels that was prominent at the 5 week timepoint however less evident at the 10 week timepoint." (PMID 37805649, 2023). "The chronic state of hyperinsulinemia interferes with the saturable transport of insulin through the BBB." (PMID 36901787, 2023). "Hyperinsulinemia and hyperamylinemia are the result of islet β-cells’ compensatory response to overcome cellular insulin resistance to glucose uptake in the MetS." (PMID 36984562, 2023). "In the state of IR, insulin secretion rises to compensate for the resistance exhibited by skeletal muscles, adipose tissue, and the liver, resulting in hyperinsulinemia." (PMID 37705037, 2023). "In rare cases, hyperinsulinemia can be attributed to specific conditions such as insulinoma, a tumor in β cells that leads to excessive insulin production, or nesidioblastosis, characterized by an abnormal increase in β-cell mass within the pancreas." (PMID 37446104, 2023). "Persistent hyperinsulinemia, impaired insulin sensitivity and disrupted glucose metabolism are recognized as a key components of EMS." (PMID 37697311, 2023). "In PCOS, miRNAs contribute to inflammation, ovarian insulin sensitivity, hyperinsulinemia, and oocyte quality." (PMID 36835989, 2023). "It is important to recognize that hyperinsulinemia, or elevated levels of insulin, is relative to the normal insulin levels observed during intervals between periodic secretions (i.e., troughs)." (PMID 37446104, 2023). "Nevertheless, cases of equines with postprandial hyperinsulinemia with normal glucose and insulin responses are known." (PMID 37628596, 2023). "In the state of IR, insulin secretion increases to compensate for the resistance of skeletal muscle, adipose tissue, and liver to insulin, which leads to hyperinsulinemia." (PMID 37258550, 2023). "The use of high doses of insulin together with glycemic support, also known as hyperinsulinemia–euglycemia therapy (HIET), was initially used in toxicology in poisoning beta-blockers and calcium antagonists." (PMID 37505522, 2023). "Administration of HMCs decreased plasma insulin, suggesting that it was effective in improving hyperinsulinemia." (PMID 37432173, 2023).
Hyperinsulinemia (continued). "Increased insulin levels (hyperinsulinemia) are necessary in order to maintain normal glucose tolerance and, therefore, hyperinsulinemia is a defining event of IR." (PMID 38001929, 2023). "Further, it is indeed of concern that almost 40% of the participants had hyperinsulinemia based on the 2-hour post glucose stimulated insulin levels." (PMID 37200851, 2023). "In the present study, control ob/ob mice demonstrated hyperinsulinemia as plasma insulin levels increased." (PMID 37432173, 2023). "Then, the pancreatic β cells try to compensate by secreting more insulin into the bloodstream, resulting in hyperinsulinemia." (PMID 36834911, 2023). "The beginning of IR frequently results in insulin paucity and a gradually dwindling blood glucose regulation, hyperinsulinemia, and increased levels of free fatty acid (FFA) circulation." (PMID 36984867, 2023). "Insulin is known to directly limit food intake by engaging complex central mechanisms, which appear dysregulated under insulin-resistant conditions or in the context of chronic hyperinsulinemia." (PMID 37819196, 2023). "Results of the study pinpointed that ponies predisposed to pasture-associated laminitis present different metabolic profiles in terms of insulin resistance, compensatory hyperinsulinemia and glucose and fat metabolism." (PMID 37628596, 2023). "IR can lead to hyperinsulinemia, which is mediated by insulin to inhibit liver glucose production imbalance, leading to an increase in blood sugar levels, which also helps to provide a substrate for DNL." (PMID 37836761, 2023). "In cases of nutritional excess, the pancreas amplifies the production and release of insulin, a hormone necessary for glucose uptake into cells and tissues, thus resulting in high circulating insulin loads (hyperinsulinemia)." (PMID 37834116, 2023). "Many women with PCOS are obese or overweight and exhibit impaired insulin metabolism, with IR and hyperinsulinemia being largely present in lean women with PCOS as well." (PMID 38004264, 2023). "Because biased agonists can induce glucose uptake through selective activation of the PI3K/AKT pathway without mitogenic stimulation, they show the potential to alleviate the adverse effects of insulin administration or hyperinsulinemia." (PMID 37779149, 2023). "In hyperinsulinemia, insulin can bind IRS1 and IRS2 on HSCs and induce collagen type 1 production via ERK- and PI3K-dependent signaling pathways." (PMID 37842470, 2023). "Metformin lowers the mitogenic activity of hyperinsulinemia through a reduction in systemic levels of insulin and insulin-like growth factor 1 (IGF-1) and displays an anti-neoplastic effect." (PMID 37834839, 2023). "A critical role for altered insulin signaling in metabolic programming has been suggested as early as the 1950s, when first correlations between maternal glucose levels, fetal hyperinsulinemia, and adverse health outcomes in the offspring were made." (PMID 37027477, 2023). "Here we considered 5—20 μU/mL as the reference range for normal fasting insulin and adopt I ≥ 25 μU/mL as the criterion of hyperinsulinemia." (PMID 36848379, 2023). "In another HFD-induced mouse model, anthocyanin (200 mg/kg/day) supplementation reduced OGTT and plasma LPS levels, reduced weight gain, improved insulin sensitivity and hyperinsulinemia." (PMID 37036026, 2023). "MCP-1 concentrations were found to be positively associated with C16:0 levels, a SFA which is known to worsen insulin sensitivity and potentiate glucose induced insulin secretion, hence favoring hyperinsulinemia." (PMID 37299395, 2023). "We found that he also had hyperinsulinemia, with a fasting glucose concentration of 230 mg/dL and a postprandial insulin level of 125 μU/mL." (PMID 37042492, 2023). "Farm accounted for the largest percentage of total variation in insulin, which is expected given the known contribution of the environment (i.e., diet and exercise) to basal insulin concentrations and hyperinsulinemia." (PMID 37148171, 2023).
Hyperinsulinemia (continued). "Resistance to insulin induces compensatory hyperinsulinemia that drives some of the phenotypic PCOS characteristics." (PMID 37791160, 2023). "Higher direct FINS levels [13.6 (8.7, 21.8) vs. 10.2 (7.6, 14.0) μIU/mL, p < 0.001)] and a higher prevalence of hyperinsulinemia (43.8% vs. 21.3%, p < 0.001) were observed in subjects with C-INS." (PMID 37324170, 2023). "Although the expression of insulin in the pancreas was increased in the tranilast-treated group, plasma insulin levels were little affected by tranilast, possibly due to the hyperinsulinemia already present in db/db mice." (PMID 36596838, 2023). "Again, the daily application of LR mitigated HFD-induced hyperinsulinemia, showing beneficial effects on insulin sensitivity." (PMID 37881580, 2023). "Their data indicate that ovaries fail to become insulin resistant, remaining sensitive to insulin and, thus, overburdened by compensatory systemic hyperinsulinemia." (PMID 36615188, 2023). "Contrarily, despite hyperinsulinemia, the rise in FFAs also reduces insulin sensitivity and blocks the insulin signal in patients with severe illnesses." (PMID 37187644, 2023). "Our results showed that only when DHT treatment and overfeeding were combined, decreased systemic insulin sensitivity and hyperinsulinemia were present, which is likely a compensatory mechanism for maintaining normal glucose levels." (PMID 37371678, 2023). "Our study thus demonstrated that hyperinsulinemia as reflected by increase in s-insulin 2 hours after OGTT was related to both AAA presence and abdominal aortic diameter, independently of both WHR and smoking." (PMID 37731907, 2023). "In this mechanism, there is a compensatory increase in insulin released from the pancreatic beta cells, leading to hyperinsulinemia." (PMID 37371662, 2023). "We previously reported that hyperinsulinemia alters insulin receptor presentation and reduces downstream insulin signaling in MBECs." (PMID 37834116, 2023). "In conjunction with a decline in the first phase of insulin secretion, we discovered an increase in hepatic insulin resistance and postprandial hyperinsulinism." (PMID 37144278, 2023). "Selective SGLT-2is are drugs that play an important role in the regulation of glucose metabolism by lowering glucose levels through an insulin-independent mechanism, reducing hyperinsulinism, and improving insulin sensitivity." (PMID 37189616, 2023). "Mutations of GLUD1, which encodes GDH, cause the second most common form of CH and is known as hyperinsulinism/hyperammonemia syndrome, because GDH is involved in amino acid-stimulated insulin secretion." (PMID 37630734, 2023). "Increased insulin level (or “hyperinsulinemia”) is a common phenomenon in pancreatic ductal adenocarcinoma (PDA) patients and signals poor clinical outcomes." (PMID 35252207, 2022). "Animal models show decreased pancreatic β-cell mass in the offspring of pregnant dams consuming a low-protein diet, which is sustained into adulthood in addition to hyperinsulinemia, and reduced insulin signaling protein expression." (PMID 35192186, 2022). "IR is a state in which peripheral target organs are both less sensitive and less responsive to endogenous or exogenous insulin, meaning that the body secretes too much insulin to maintain blood glucose stability, resulting in hyperinsulinemia." (PMID 36072812, 2022). "The sensitivity of tissue to insulin decreased in the IR state, and compensatory hyperinsulinemia occurred." (PMID 36386912, 2022). "Insulin dysregulation (ID), characterized by basal hyperinsulinemia and an exacerbated insulin response to an oral or intravenous glycemic challenge, remains a prevalent clinical problem in the equine industry." (PMID 35711802, 2022). "For example, in the case of hypothyroidism, glucose uptake in muscle and adipose tissue is resistant to insulin, resulting in hyperinsulinemia and insulin resistance." (PMID 36176844, 2022).
Hyperinsulinemia (continued). "Hyperinsulinemia has been shown to promote adipose tissue inflammation in mice, whereas a decrease in circulating insulin levels lead to a decrease in the expression of pro-inflammatory markers and macrophage content in adipose tissue." (PMID 36589440, 2022). "For instance, a recent study showed that AD patients exhibit a reduced peripheral insulin sensitivity and hyperinsulinemia, both under fasting state as well as in response to an oral glucose tolerance test." (PMID 35805109, 2022). "The reduced tissue sensitivity to insulin resulted in an increase in glucose and insulin levels, and chronic hyperinsulinemia promoted the secretion of insulin-like growth factor 1 (IGF-1) and a decrease in the production of IGF-binding proteins." (PMID 35409299, 2022). "In an attempt to overcome the inherent insulin resistance, the pancreas increases its insulin production, leading to hyperinsulinemia." (PMID 35244142, 2022). "Kahleova et al46 also indicated that INS secretion was negatively correlated with PP secretion in T2DM patients with hyperinsulinemia." (PMID 35437937, 2022). "Probably, the reduced insulin sensitivity leads to an inevitable compensatory hyperinsulinemia, and this contributes to the development of hyperandrogenism through a chronic stimulus directed toward the cells of the ovarian theca." (PMID 35956124, 2022). "How this relates to effective weight management is unclear, especially in older people, who are highly vulnerable to hyperinsulinemia and in whom neural target systems of insulin action undergo age-related changes." (PMID 36170006, 2022). "Hyperinsulinemia can be defined as excess circulating insulin beyond what is required for maintaining glucose homeostasis." (PMID 35189981, 2022). "The results showed that p-DRP1 S616 was significantly increased, contrary MFN2 expression was decreased in both BV2 cells and primary microglia treated by insulin, suggesting hyperinsulinemia made mitochondrial fission and fusion out of balance in microglia." (PMID 36466168, 2022). "We also characterized the insulin dose‐ and time‐dependent signaling in our in vitro hyperinsulinemia model (200 nM insulin)." (PMID 34921686, 2022). "We studied the expression of THRSP before and during euglycemic hyperinsulinemia in vivo and found that insulin significantly induced THRSP expression, which was enhanced in subjects with high insulin sensitivity." (PMID 35715726, 2022). "We therefore, performed hyperinsulinemic‐euglycemic clamps, where euglycemic hyperinsulinemia was confirmed by stable blood glucose levels in mice subjected to a variable infusion of glucose and a constant infusion of insulin for 120 min." (PMID 36073057, 2022). "The role of ZIP14 in glucose homeostasis has been highlighted in ZIP14 knockout (KO) mice which display hyperinsulinemia and impaired insulin secretion when fed a high glucose diet." (PMID 35784893, 2022). "It seems that KCNJ15 works as a feedback control to protect against high insulin in the blood (hyperinsulinemia)." (PMID 35723340, 2022). "In order to verify the direct effect of hyperinsulinemia on liver development, HepG2 cells were cultured in a medium containing different insulin concentrations for 24 h." (PMID 35432202, 2022). "Sodium-glucose cotransporter 2 (SGLT2) inhibitors have a unique mode of action to lower plasma glucose levels in an insulin-independent manner via an increase in urinary glucose excretion, which in turn can mitigate glucotoxicity and hyperinsulinemia." (PMID 35941584, 2022). "The passage of amino acids through the placenta regulates insulin (hyperinsulinemia increases the transfer), and the fetal pancreas responds to an increase in the concentration of amino acids and glucose by producing insulin." (PMID 35334589, 2022). "In all six studies with available insulin data, hyperinsulinemia relative to the respective control was observed." (PMID 36003651, 2022).